ZNF688 (zinc finger protein 688)
Description:
May be involved in transcriptional regulation.
Tractability: Antibody: the Human Protein Atlas places it where antibodies can reach.
Gene: Protein-coding gene on chromosome 16 (30,569,281 to 30,572,734, reverse strand). Ensembl gene ENSG00000229809.
Subcellular location: Nucleus
Subcellular location (Human Protein Atlas): Nucleoplasm; Cell Junctions; Plasma membrane
Pathways (Reactome):
Gene expression (Transcription): Generic Transcription Pathway
Gene Ontology:
Molecular function: protein binding; DNA-binding transcription factor activity; DNA-binding transcription repressor activity, RNA polymerase II-specific; RNA polymerase II cis-regulatory region sequence-specific DNA binding
Biological process: negative regulation of transcription by RNA polymerase II; regulation of DNA-templated transcription
Cellular component: nucleus
Genetic constraint (gnomAD): Loss-of-function variants: 13 observed, 15.17 expected, observed/expected ratio (o/e) 0.86, 90% interval 0.56 to 1.36. The upper end of that interval is the gene's LOEUF score, 1.36, which puts it in group 5 of 6, group 1 being the genes least tolerant of losing a copy. Missense variants: 381 observed, 368.77 expected, observed/expected ratio (o/e) 1.03, 90% interval 0.95 to 1.12. Synonymous variants: 160 observed, 154.05 expected, observed/expected ratio (o/e) 1.04, 90% interval 0.91 to 1.18.
Homologues: Orthologues: chimpanzee ZNF688 (100% identical), pig ZNF688 (83% identical), guinea pig ZNF688 (78% identical), mouse Zfp688 (75% identical), rat Zfp688 (74% identical), zebrafish si:dkey-89b17.4 (17% identical), zebrafish znf646 (16% identical), Drosophila melanogaster az2 (12% identical), zebrafish znf576.1 (12% identical), Drosophila melanogaster CG1602 (12% identical), Drosophila melanogaster CG30020 (11% identical), Drosophila melanogaster mld (11% identical), and 4 more. Paralogues in human: ZNF785 (54% identical), ZNF764 (49% identical), ZNF689 (45% identical), ZNF747 (43% identical), ZNF574 (22% identical), ZFP92 (22% identical), ZNF282 (22% identical), ZNF142 (20% identical), ZBTB24 (20% identical), ZBTB48 (19% identical), ZNF420 (19% identical), ZNF84 (19% identical), and 24 more.
Diseases named in the same sentence as ZNF688 in open-access papers:
ZNF688 is named in the same sentence as 1 disease in open-access papers, as found by Europe PMC text mining. Sharing a sentence is not in itself a finding about the gene and the disease.
ZNF688 shares sentences with these, for which no sentence is quoted: sarcoidosis (1 paper).